HIPK3 (homeodomain interacting protein kinase 3)
Description:
Serine/threonine-protein kinase involved in transcription regulation, apoptosis and steroidogenic gene expression. Phosphorylates JUN and RUNX2. Seems to negatively regulate apoptosis by promoting FADD phosphorylation. Enhances androgen receptor-mediated transcription. May act as a transcriptional corepressor for NK homeodomain transcription factors. The phosphorylation of NR5A1 activates SF1 leading to increased steroidogenic gene expression upon cAMP signaling pathway stimulation. In osteoblasts, supports transcription activation: phosphorylates RUNX2 that synergizes with SPEN/MINT to enhance FGFR2-mediated activation of the osteocalcin FGF-responsive element (OCFRE).
Synonyms: DYRK6; FIST3; PKY; YAK1
Tractability: Small molecule: a structure with a bound ligand is known; a high-quality ligand is known; it belongs to a druggable protein family. Antibody: its Gene Ontology location is reachable by antibodies, with high confidence. PROTAC: UniProt records ubiquitination sites on it; ubiquitination databases record sites on it; a small molecule that binds it is known.
Target class: CMGC protein kinase group; CMGC protein kinase HIPK subfamily; Enzyme; Kinase; CMGC protein kinase DYRK family; Protein Kinase
Gene: Protein-coding gene on chromosome 11 (33,256,672 to 33,357,023, forward strand). Ensembl gene ENSG00000110422.
Subcellular location: Cytoplasm; Nucleus
Subcellular location (Human Protein Atlas): Cytosol; Nuclear bodies
Gene Ontology:
Molecular function: protein kinase activity; protein serine/threonine kinase activity; ATP binding; protein serine kinase activity
Biological process: mRNA transcription; negative regulation of apoptotic process; protein phosphorylation; negative regulation of JUN kinase activity; peptidyl-serine phosphorylation; peptidyl-threonine phosphorylation
Cellular component: cytosol; nuclear body; cytoplasm; nucleus; PML body; nucleoplasm
Genetic constraint (gnomAD): Loss-of-function variants: 37 observed, 104.41 expected, observed/expected ratio (o/e) 0.35, 90% interval 0.27 to 0.47. The upper end of that interval is the gene's LOEUF score, 0.47, which puts it in group 2 of 6, group 1 being the genes least tolerant of losing a copy. Missense variants: 1,156 observed, 1,367.1 expected, observed/expected ratio (o/e) 0.85, 90% interval 0.81 to 0.89. Synonymous variants: 435 observed, 490.51 expected, observed/expected ratio (o/e) 0.89, 90% interval 0.82 to 0.96.
Homologues: Orthologues: chimpanzee HIPK3 (99% identical), macaque HIPK3 (99% identical), guinea pig HIPK3 (96% identical), dog HIPK3 (95% identical), pig HIPK3 (95% identical), rabbit HIPK3 (95% identical), mouse Hipk3 (91% identical), rat Hipk3 (90% identical), tropical clawed frog hipk3 (69% identical), zebrafish hipk3b (63% identical), Drosophila melanogaster Hipk (38% identical), Caenorhabditis elegans Y111B2A.1 (7% identical), and 1 more. Paralogues in human: HIPK2 (51% identical), HIPK1 (48% identical), HIPK4 (19% identical), DYRK1A (15% identical), DYRK2 (13% identical), DYRK1B (13% identical), DYRK4 (12% identical), DYRK3 (12% identical), CLK2 (10% identical), CLK1 (10% identical), CLK4 (10% identical), CLK3 (9% identical).
Diseases named in the same sentence as HIPK3 in open-access papers:
HIPK3 is named in the same sentence as 71 diseases in open-access papers, as found by Europe PMC text mining. Sharing a sentence is not in itself a finding about the gene and the disease. The quoted sentences say what the papers report.
osteosarcoma (8 papers, 2016 to 2022). A usually aggressive malignant bone-forming mesenchymal neoplasm, predominantly affecting adolescents and young adults. "Hsa_hsa_circ_0000285, a circRNA generated from homeodomain interacting protein kinase 3 (HIPK3), suppresses the progression of various cancers, including cervical cancer, osteosarcoma, thyroid cancer, and hepatocellular carcinoma." (PMID 35535385, 2022). "Circular RNA circ-HIPK3 is downregulated and suppresses cell proliferation, migration, and invasion in osteosarcoma and shows a significantly hypomethylated m6A peak in the tumor group." (PMID 34868913, 2021). "In fact, overexpression of HIPK3 protects osteosarcoma cells from cisplatin-induced death in vitro and in vivo." (PMID 32260415, 2020). "For instance, circ-HIPK3 was reported as an oncogene in prostate cancer, hepatocellular carcinoma and colorectal cancer, but as a tumor inhibitor in osteosarcoma, ovarian cancer and bladder cancer." (PMID 31631067, 2019). "HIPK3 expression level refers to prognosis and sensitivity to chemotherapy, higher HIPK3 expression with badly prognosis and chemoresistance in osteosarcoma and prostate cancer." (PMID 29700213, 2019). "miR-382 overexpression restrained osteosarcoma cell proliferation and chemoresistance by regulating HIPK3 and KLF12." (PMID 29113367, 2017).
bladder cancer (7 papers, 2019 to 2025). "We found that a low expression of METTL14 (a m6A methyltransferase), SMPD4, and SGK2, but a high expression of ALKBH5 (a m6A de methyltransferase), LINC00482, and HIPK3, showed a tendency to associate with worse overall survival in bladder cancer patients." (PMID 34868913, 2021). "Circular RNA HIPK3 (circHIPK3) mediates the progression of multiple cancers, including bladder cancer, by regulating cell migration, autophagy and epithelial mesenchymal transition." (PMID 37269429, 2023). "Another circRNA involved in the metastatic EMT of bladder cancer is circ-HIPK3, produced from exon 2 of the homeodomain-interacting protein kinase 3 (HIPK3) gene, also known as bladder cancer-related circular RNA-2 (BCRC-2)." (PMID 35626752, 2022). "CircHIPK3 (circRNA ID: hsa_circ_0000284), also named bladder cancer-related circular RNA-2 (BCRC-2), originates from the second exon of Homeodomain-interacting protein kinase 3 (HIPK3) gene and consists of 1099 nucleotides in length." (PMID 32194801, 2020). "Mechanistically, circ-HIPK3 enrichment can abundantly sponge miR-558 to decrease heparanase (HPSE), VEGF, and matrix metallopeptidase 9 (MMP9) levels, thus effectively suppressing the invasive abilities and angiogenesis of bladder cancer cells." (PMID 31937318, 2020).
breast cancer (7 papers, 2020 to 2025). A primary or metastatic malignant neoplasm involving the breast. "FOXO3, known as a tumor suppressor, acts via decreasing cell proliferation and metastasis and increasing apoptosis in various cancers, including breast cancer; however, the role of HIPK3 has received less attention." (PMID 36132137, 2022). "Interestingly, AR signaling in ER+ breast cancer is thought to be associated with favorable prognosis, and the reduction of HIPK3 and NCOA4 may negatively affect AR signaling and ER+ breast cancer prognosis." (PMID 35311114, 2022).
cervical cancer (7 papers, 2015 to 2025). A primary or metastatic malignant neoplasm involving the cervix. "miR-200b was also shown to be hypomethylated and target Homeodomain-interacting protein kinase 3 (HIPK3) in cervical cancer." (PMID 36879084, 2023). "It was reported that circ-HIPK3/miR-338-3p promote cell development in cervical cancer, through regulating HIF-1α mediated EMT." (PMID 33109773, 2020). "In cervical cancer, circCCDC134, circ_0004543, and circ-HIPK3 all upregulate the expression of HIF-1α by acting as miRNA sponges, thus promoting the proliferation, migration, and invasion of cervical cancer cells and thereby accelerating tumor growth and metastasis." (PMID 40004471, 2025). "Circ_HIPK3 induced EMT of cervical cancer via targeting mir-338-3p." (PMID 33109773, 2020). "Similarly, upregulated circ-HIPK3 in cervical cancer cells sequesters miR-338-3p to increase the expression of HIF-1α, consequently enhancing the proliferation, colony formation, migration, and invasiveness of cervical cancer cells while suppressing their apoptosis." (PMID 40004471, 2025).
hepatocellular carcinoma (7 papers, 2011 to 2025). A malignant tumor that arises from hepatocytes. "It has been reported that miR-582-3p can affect the progression of hepatocellular carcinoma cells by targeting circRNA HIPK3 and circRNA PTPRA, but the regulation of targeted mRNA has not been reported Therefore, miR-582-3p was selected for further study in this project." (PMID 35386287, 2022). "This study is based on our initial finding that amiloride changed the alternative RNA splicing of BCL-X, HIPK3 and RON/MISTR1 transcripts from oncogenic patterns towards normal patterns in human hepatocellular carcinoma Huh-7 cells." (PMID 21694768, 2011). "Screening small molecules and drugs for modulating RNA splicing in human hepatocellular carcinoma cell line Huh-7, we discovered that amiloride, distinct from four pH-affecting amiloride analogues, could “normalize” the splicing of BCL-X, HIPK3 and RON/MISTR1 transcripts." (PMID 21694768, 2011).
lung carcinoma (7 papers, 2020 to 2024). "Specifically, circHIPK3, from the HIPK3 gene, has been closely associated with lung cancer pathogenesis, highlighting its potential as a diagnostic biomarker." (PMID 39273053, 2024). "Circular RNA HIPK3 (circHIPK3) is derived from chromosomal region 11p13 and originates from the second exon of HIPK3; it has been reported in a variety of cancers, such as gastric cancer and lung cancer." (PMID 37269429, 2023). "CircHIPK3 is derived from exons 7–11 of homeodomain-interacting protein kinase 3 (HIPK3), which is highly expressed in lung cancer tissues and cells." (PMID 36142352, 2022). "The expression pattern of circRNAs HIPK3 and PTK2 was determined using quantitative polymerase chain reaction (qPCR) in lung cancer patient samples and cell lines." (PMID 34326381, 2021). "For instance, the circ-HIPK3 transcript acts as a microRNA-124 (miR-124) sponge and regulates the expression of miR-124 mRNA targets, including SphK1, CDK4, and STAT3, in lung cancer cells." (PMID 32692763, 2020).
colorectal cancer (6 papers, 2019 to 2023). A primary or metastatic malignant neoplasm that affects the colon or rectum. "Flow cytometry results agreed with immunoblotting results, thereby further consolidating the finding that overexpression of HIPK3 enhances intrinsic apoptosis in colorectal cancer cells." (PMID 35096570, 2021). "Overexpression of HIPK3 traps a metabolically reprogrammed state in colorectal cancer where its metabolism shifts from glycolysis to oxidative phosphorylation." (PMID 35096570, 2021). "Our findings unraveled a relationship between 101-3p/HIPK3 axis with metabolic reprogramming in colorectal cancer." (PMID 35096570, 2021). "This study unraveled an oncogenic nature of the exosomal 101-3p and suggested a relationship between the 101-3p-HIPK3 axis and metabolic homeostasis in colorectal cancer." (PMID 35096570, 2021). "We then examined the tumor suppressive potential of HIPK3 in two colorectal cancer cell lines, HCT116 and SW480." (PMID 35096570, 2021). "Expression of all three glycolytic enzymes was inhibited by HIPK3 overexpression, implicating a regulatory role of HIPK3 in colorectal cancer’s metabolism." (PMID 35096570, 2021). "So far, the involvement of a number of circular RNAs including ciRS-7-A, circITGA7, PIP5K1A, GLIS2, and HIPK3 in the development of colorectal cancer has been identified." (PMID 34479583, 2021). "We believe inhibiting 101-3p or any other means to enhance HIPK3 expression is a feasible approach to sensitize colorectal cancer to chemotherapy." (PMID 35096570, 2021). "Collectively, these findings revealed that miR-382 inhibits migration and enhances chemosensitivity by targeting KLF12 and HIPK3 in colorectal cancer." (PMID 29700213, 2019). "Moreover, overexpression of HIPK3 suppressed cell proliferation and migration in CCA cells, particularly in KKU-100 cells, agreeing with that in colorectal cancer in which overexpression of HIPK3 inhibited cancer cell growth and migration." (PMID 38105269, 2023). "To elaborate, because 101-3p did not affect circHIPK3 expression, HIPK3 inhibition by 101-3p is positively correlated to glycolytic capacity in colorectal cancer." (PMID 35096570, 2021). "HIPK3 promotes FADD phosphorylation and metabolic reprogramming in colorectal cancer." (PMID 35096570, 2021). "Furthermore, we identified Krüppel-like factor 12 (KLF12) and homeodomain-interacting protein kinase 3 (HIPK3) as the target of miR-382, and miR-382 rescued the promotion effect of KFL12 on migration and enhanced chemosensitivity in colorectal cancer cell lines." (PMID 29700213, 2019).
prostate carcinoma (6 papers, 2019 to 2025). A carcinoma that arises from epithelial cells of the prostate gland. "In prostate cancer, HIPK3-mediated FADD phosphorylation is crucial for FAS-induced apoptosis." (PMID 40280416, 2025). "Notably, a previous study reported that JNK regulated HIPK3 expression in prostate carcinoma cells, suggesting the existence of a positive feedback loop between HIPK3 and JNK." (PMID 40280416, 2025). "In prostate cancer, JNK activity increases the expression of HIPK3 and promotes resistance to FAS receptor-mediated apoptosis." (PMID 32260415, 2020).
gastric cancer (5 papers, 2017 to 2025). A primary or metastatic malignant neoplasm involving the stomach. "There was also circ-HIPK3 upregulation in gastric cancer (GC) tissues in comparison with normal margins." (PMID 33827418, 2021). "Additionally, low HIPK3 levels contribute to cisplatin resistance in gastric cancer, with overexpression of HIPK3 overcoming this resistance." (PMID 40280416, 2025). "Most of the highest expressed circRNA genes in gastric cancer samples are also present in tumor-adjacent tissue (CFLAR, CORO1C, HIPK3, ASXL1 and SFMBT2)." (PMID 29109417, 2017).
glioma (5 papers, 2020 to 2025). A benign or malignant brain and spinal cord tumor that arises from glial cells (astrocytes, oligodendrocytes, ependymal cells). "Circ-HIPK3 enhances glioma cell proliferation and invasion, as well as tumor propagation in vivo, according to functional analysis." (PMID 35883576, 2022). "Additionally, exosomal circ-HIPK3 from TMZ-resistant glioma cells regulates glioma via the miR-421/ZIC5 axis, thereby enhancing its drug resistance." (PMID 37779868, 2023). "Circ-HIPK3 may enhance IGF2BP3 expression in glioma cells by interacting with miR-654." (PMID 35883576, 2022). "This experimental mechanism suggests that exosomal circ‐HIPK3 enhances cell advancement and TMZ resistance in TMZ‐resistant gliomas by regulating the miR‐421/ZIC5 axis." (PMID 39950738, 2025). "Exosome-mediated circ-HIPK3 enhances TMZ resistance via modulating the miR-421/ZIC5 axis and promotes tumorigenesis in vitro and in vivo; its expression in serum exosomes can be used as a biomarker for diagnosis of TMZ-resistant glioma." (PMID 35382838, 2022). "Overall, these data indicate that circ-HIPK3 promotes glioma progression by targeting miR-654 from IGF2BP3, implying that circ-HIPK3 may be a therapeutic target for glioma." (PMID 35883576, 2022).
myocardial infarction (4 papers, 2019 to 2025). Gross necrosis of the myocardium, as a result of interruption of the blood supply to the area, as in coronary thrombosis. "In our study, we found that circ-HIPK3 can be upregulated significantly in heart post myocardial infarction (MI) and affected the Ca2+ in cytoplasm via circ-HIPK3 - miR-17-3p - ADCY6 axis." (PMID 31595165, 2019). "Our study indicates that miR-21 attenuates FAS-mediated cardiomyocyte apoptosis by regulating HIPK3 expression, which could eventually have important clinical implications for patients with acute myocardial infarction." (PMID 37581369, 2023). "In addition, HIPK3 regulated cardiomyocyte apoptosis in a cell model of myocardial infarction; however, there are few studies investigating the effect of HIPK3 on IRI-induced cardiomyocyte apoptosis." (PMID 37581369, 2023). "Downregulating the CREB1-mediated circ-HIPK3 expression level could reduce the degree of fibrosis after myocardial infarction and maintain cardiac function." (PMID 34925046, 2021).
ovarian carcinoma (4 papers, 2019 to 2020). A malignant neoplasm originating from the surface ovarian epithelium. "For example, circEXOC6B and circN4BP2L2 may act as novel prognostic biomarkers in patients with epithelial ovarian cancer, circ_0051240 promotes cell proliferation, migration and invasion in ovarian cancer, and circ-HIPK3 is an important regulator of ovarian cancer progression." (PMID 32690086, 2020). "Overall, these observations suggest that ILK regulates the JNK/c-JUN pathway in cisplatin-resistant ovarian cancer via modulation of DUSP8, MARVELD3, PDCD4, MAPK8IP1, MAPK8IP2, and HIPK3." (PMID 32260415, 2020).
Sepsis (4 papers, 2022 to 2025). Sepsis is defined as life-threatening organ dysfunction caused by a dysregulated host response to infection. "Similar findings were noted for circ-HIPK3 in a murine model of AKI induced by Candida albicans, where the downregulation of circ-HIPK3 ameliorated the inflammatory response to sepsis, with reduced levels of IL-6 and TNF-α but increased levels of IL-10." (PMID 35955644, 2022). "This research intended to elucidate the mechanism of circular RNA HIPK3 (circHIPK3) in sepsis-engendered AKI." (PMID 35148669, 2022). "However, in contrast to our findings, another investigation showed that HIPK3 inhibited JNK signaling in monocytes from a rat sepsis model induced by cecal ligation and puncture." (PMID 40280416, 2025).
heart failure (3 papers, 2019 to 2024). Inability of the heart to pump blood at an adequate rate to meet tissue metabolic requirements. "Circ-HIPK3, for example, exacerbates the effect of adrenaline on heart failure through modulating the miR-17-3p/ADCY6 axis." (PMID 36800233, 2023). "Circ-HIPK3 interacts with miR-17-3p to elevate ADCY6 expression, thereby strengthening adrenaline-mediated effects in heart failure." (PMID 36800233, 2023). "Like circRNA Slc8a1, circRNA HIPK3 has been shown to sponge miR-133a in a model of MI, enhancing Notch1 and connective tissue growth factor (CTGF) expression thereby driving proliferation, migration, and fibrosis in a manner protective against heart failure." (PMID 38485860, 2024). "Drugs targeting circRNA HIPK3 could be potent modulators of TGFβ-driven fibrosis and heart failure; however, its context dependence may not be completely understood." (PMID 38485860, 2024).
Huntington disease (3 papers, 2017 to 2022). Huntington disease (HD) is a rare neurodegenerative disorder of the central nervous system characterized by unwanted choreatic movements, behavioral and psychiatric disturbances and dementia. "In addition, HIPK3 may also be a novel kinase regulator of autophagy in Huntington disease (HD) cells, contributing to the accumulation of proteins and disease progression." (PMID 36703984, 2022).